IL17A (interleukin 17A)
Diseases named in the same sentence as IL17A in open-access papers (continued):
Sharing a sentence is not in itself a finding about the gene and the disease.
cutaneous candidiasis (8 papers, 2013 to 2024). Candidiasis of the skin manifested as eczema-like lesions of the interdigital spaces, perleche, or chronic paronychia. "Human data and results obtained from mouse models of OPC and cutaneous candidiasis suggest that IL-17A and IL-17F are the predominant IL-17 family of cytokines for the protection against C. albicans." (PMID 26274976, 2015). "The similarities between WT littermate controls and IL-17RE-/- mice indicate that IL-17C signaling via IL-17RE is not essential for protection from or the resolution of cutaneous candidiasis, whereas IL-17A signaling through IL-17RA/IL-17RC is nonredundant." (PMID 25849644, 2015).
fungal keratitis (8 papers, 2015 to 2025). "In a model of fungal keratitis, IL-17A was protective, although the cellular sources of IL-17A attributed to this protection included neutrophils in addition to Th17 cells." (PMID 25954267, 2015).
ileitis (8 papers, 2013 to 2025). "Neutrophil IL-17A production in the peritoneal cavity was shown to be microbiota dependent, as was ER-stress induced increased ileal IL-23 expression, MLN IL-17A expression, goblet cell loss, and ileitis development." (PMID 34267743, 2021). "We showed before that oral infection with cysts of T. gondii (76K strain) caused upregulation of IL-1β and IL-17A in the ileum with acute lethal ileitis in sensitive B6 mice." (PMID 31057534, 2019). "Moreover, an enhanced Th17 response with elevated IL-17A and IL-22 expression has been reported upon T. gondii infection with diminished ileitis in IL-17RA and IL-22 deficient mice." (PMID 31057534, 2019).
infarction (8 papers, 2012 to 2023). A localised pathological necrosis of tissue resulting from obstruction of the blood supply usually by a thrombus, an embolus, or vascular torsion. "Most IL-17A–producing cells in the peripheral blood after infarction are CD3+ T cells, with the majority of them being γδT cells, which are the main source of IL-17 in the blood after infarction, instead of Th17 cells." (PMID 36066993, 2022).
infectious colitis (8 papers, 2014 to 2026). A viral or bacterial infectious process affecting the large intestine. "Infectious colitis is associated with a protective mucosal state where IL-17A is a key contributor in a broader protective response, whereas sterile colitis is associated with persistent epithelial barrier dysfunction that is associated with increased susceptibility to subsequent infection." (PMID 42269772, 2026). "Blocking IL-17A could, therefore, increase the risk of infectious colitis." (PMID 38060157, 2024). "The role of IL-17A inhibitors in the pathogenesis of infectious colitis and new-onset IBD is not fully understood and requires further research." (PMID 38060157, 2024). "Therefore, there might be an increased risk for infectious colitis during IL-17A-inhibitor therapy." (PMID 38060157, 2024). "In a model of Citrobacter rodentium-driven infectious colitis, IL-33 inhibited the differentiation of IL-17A-producing CD4+ T cells, which have the potential to reverse the negative effect of IL-33 during infection." (PMID 36570798, 2022).
Listeria infection (8 papers, 2011 to 2020). "Considering the reduced Th17 immunocompetency as the main risk factor of listeriosis, biomarkers of poor prognosis, such as high sensitivity to hypervirulent Listeria clones, low IL-17A/IL-6 ratios, and anti-GAPDH1–22 antibodies should assist in reducing listeriosis incidence." (PMID 27965668, 2016). "IL-17A has been shown to directly stimulate DC activity, thus promoting protective immunity in Listeria infection." (PMID 31244826, 2019). "Accordingly, we conclude that low levels of anti-GAPDH1–22 antibodies, together with low IL-17A levels, are two valid immunological biomarkers of poor prognosis in listeriosis patients with tumors under chemotherapeutic treatment." (PMID 27965668, 2016). "However, listeriosis patients with autoimmune diseases or miscarriages showed high levels of IL-17A/IL-6 ratios." (PMID 27965668, 2016). "In addition, listeriosis patients with cancer present low IL-17A/IL-6 ratios and significantly reduced levels of anti-GAPDH1–22 antibodies, identified as two novel biomarkers of poor prognosis." (PMID 27965668, 2016). "In fact, IFN-αβR KO mice induced more IL-17A in response to Francisella and Listeria infections." (PMID 21829705, 2011).
Mycobacterium infection (8 papers, 2016 to 2025). Infections with bacteria of the genus Mycobacterium. "In human, RORC mutant patients showed decrease of IL‐17A expression by T cells, which resulted in increased susceptibility to mycobacterial infection with decreased anti‐mycobacterial Th1 response." (PMID 27980775, 2016). "Importance of IL‐17A in Th1‐mediated protective immunity against mycobacterial infection was also indicated in human RORC mutant patients." (PMID 27980775, 2016). "From those observations, we reasoned that IL‐17A‐producing TCR γδ+ T cells exist as lung resident lymphocytes, and they expand or are further accumulated in the lung after mycobacterial infection." (PMID 27980775, 2016). "Although the impact of IL-17A and IL-22 on the immune response to MAC infection is not clearly understood yet, in a murine model, both IL-17A and IL-22 were shown to contribute to granuloma formation by M. tuberculosis, which appears to have a protective function during mycobacterial infection." (PMID 29401501, 2018).
Mycoplasma infection (8 papers, 2016 to 2025). "In Mycoplasma infections, IL-17A consistently displays pathogenic potential across multiple clinical contexts." (PMID 41438744, 2025). "However, IL-17A’s role is highly context dependent; in mycoplasma infections, it exhibits paradoxical and often pathogenic effects." (PMID 41438744, 2025). "We delineate the duality of IL-17A in mycoplasma infections, mediating both protection and tissue damage, and critically examine its implications for vaccine design." (PMID 41438744, 2025). "Given the previous correlations between disease severity and IL-17A levels during Mycoplasma infection, and the elevated IL-17A in LAMPs-vaccinated/Mp-challenged animals, we wished to determine the cellular sources of IL-17A in our model." (PMID 35906257, 2022).
mycoplasma pneumonia (8 papers, 2017 to 2025). "In addition, ATF3 facilitates the pathogen clearance in S. pneumoniae infection by promoting IL-17A production in γδ T cells, and it inhibits the secretion of inflammatory cytokines induced by Mycoplasma pneumonia in vitro and in vivo." (PMID 34135870, 2021). "Furthermore, significantly higher frequencies of Th17 cells, which induce neutrophil infiltration into sites of inflammation via the production of IL-17, and higher levels of IL-17A have been observed in patients with refractory mycoplasma pneumonia." (PMID 33520736, 2020).
necrotizing enterocolitis (8 papers, 2018 to 2026). Necrotizing enterocolitis (NEC) is a devastating disease that affects mostly the intestine of premature infants. "IL-17A is a cytokine involved in intestinal inflammation and is increased in neonatal necrotizing enterocolitis in humans and in murine models." (PMID 39624085, 2024). "Beside RA, IL17A (rs2275913) polymorphism has been reported to be associated with the development of rheumatic heart disease in south Indian population, and a variant of IL17F (rs763780) may contribute to the development of necrotizing enterocolitis." (PMID 30658595, 2019).
osteitis (8 papers, 2015 to 2026). "In conclusion, the GTA haplotype of IL17A rs4711998, IL17A rs8193036 and IL17A rs2275913 was significantly associated with osteitis after BCG vaccination as newborn." (PMID 28916742, 2017).
peripheral nerve injury (8 papers, 2013 to 2025). Injury to a peripheral nerve. "Peripheral nerve injury and formalin injection both drive macrophages in the DRG to release IL-23, which further induces IL-17A release from macrophages." (PMID 40671873, 2025).
proliferative diabetic retinopathy (8 papers, 2017 to 2025). Advanced retinopathy due to diabetes mellitus characterized by the formation of new vessels in the retina. "Multiple regression analysis of IL-17A level in vitreous fluid with cytokine levels in aqueous humor of patients with proliferative diabetic retinopathy (PDR)." (PMID 28558009, 2017). "Multiple regression analysis of IL-17A level with other cytokine levels in aqueous humor and vitreous fluid of patients with proliferative diabetic retinopathy (PDR)." (PMID 28558009, 2017). "Multiple regression analysis of IL-17A level in aqueous humor with cytokine levels in vitreous fluid of patients with proliferative diabetic retinopathy (PDR)." (PMID 28558009, 2017). "Additionally, serum IL-17 levels are elevated in patients with DR compared to controls, and increased IL-17A level is detected in the ocular fluid of eyes with proliferative diabetic retinopathy (PDR)." (PMID 38887289, 2024). "Still, additional therapeutic studies are required to determine if anti-IL-17A could be a good therapeutic candidate for non-proliferative diabetic retinopathy." (PMID 36674854, 2023). "Hence, the role of IL-17A in vascular angiogenesis, neovascularization, and the onset of proliferative diabetic retinopathy was unclear." (PMID 36675261, 2023). "Taken together, we further validate that anti-IL-17A could be a potentially novel therapeutic for non-proliferative diabetic retinopathy in both Type I and Type II diabetics." (PMID 36674854, 2023). "Yet, proof-of-principle that IL-17A could be a good therapeutic target for non-proliferative diabetic retinopathy was provided." (PMID 36674854, 2023). "Additionally, a study of 64 participants found significantly higher concentrations of cytokines such as IL6, IL12, IL17A, and TNFα in DR patients compared to healthy controls, with the highest cytokine levels observed in the non-proliferative diabetic retinopathy (NPDR) group." (PMID 40136531, 2025). "Their study found that higher serum IL17A levels were significantly associated with more severe DR, with logistic regression analysis confirming a higher risk of both non-proliferative and proliferative diabetic retinopathy in individuals with elevated IL17A levels." (PMID 40136531, 2025). "Thus, we cannot fully conclude that IL-17A plays a role in proliferative diabetic retinopathy." (PMID 36675261, 2023). "When IL-17A binds to its IL17R receptor, an Act1-FADD signaling cascade induces retinal endothelial cell death, vascular impairment, and the onset of non-proliferative diabetic retinopathy in diabetic mice." (PMID 32429598, 2020).
Respiratory tract infection (8 papers, 2019 to 2023). An infection of the upper or lower respiratory tract. "Thus, it can be concluded that IL-17A concentration in airway was associated with severe respiratory tract infection." (PMID 36793128, 2023).
rheumatic heart disease (8 papers, 2019 to 2024). An autoinflammatory condition following an infection with Group A Beta Hemolytic Streptococcus (GABHS), in which the heart is attacked by antibodies formed in reaction to a recent GABHS infection. "For example, group G Streptococcus induced an autoimmune carditis mediated by IL-17A and interferon gamma in the Lewis rat model of rheumatic heart disease." (PMID 32733424, 2020). "Furthermore, our study links Th17 cells/IL-17A with rheumatic carditis and demonstrates the coincidence of IL-17A and IFN-γ with IgG2 deposition, the most prominent IgG subclass on RHD derived valve tissues." (PMID 36815140, 2022).
sporotrichosis (8 papers, 2018 to 2025). The commonest and least serious of the deep mycoses, characterized by nodular lesions of the cutaneous and subcutaneous tissues. "With higher levels of IFN-β, IL-17A and IL-1β and increased numbers of CD4+ T cells in the lymph nodes and spleen, ZR8 peptide is the best vaccine candidate against subcutaneous sporotrichosis." (PMID 29520092, 2018).
thymoma (8 papers, 2010 to 2025). A neoplasm arising from the epithelial cells of the thymus. "Kisand and colleagues reported on a cohort of 162 patients with APECED and described anti-IL-17A, IL-17F and/or IL-22 AAbs in over 90% of cases, and additionally detected high titer IL-17A and IL-22 AAbs in two patients with thymoma and CMC." (PMID 31557985, 2016). "IL-17 has been reported to be increased in the sera (IL-17) and PBMC culture of patients with thymoma (IL-17A) only." (PMID 25893403, 2015). "EL4 mouse thymoma cells were transfected with reporter constructs containing the Il17a promoter, with or without Fak siRNA, and then treated with phorbol 12-myristate 13-acetate (PMA) and ionomycin." (PMID 41050684, 2025). "At least in APECED and thymoma, the development of cytokine autoantibodies is not limited to IFNs as they develop autoantibodies to other cytokines including IL-17A, IL-17F, IL-22, IL-12, and IL-1A." (PMID 40304722, 2025).
triple-negative breast carcinoma (8 papers, 2020 to 2025). An invasive breast carcinoma which is negative for expression of estrogen receptor (ER), progesterone receptor (PR), and human epidermal growth factor receptor 2 (HER2). "More patients and a longer follow-up will be needed to verify the possible influence of serum IL-17A levels preoperatively or during treatment on triple negative breast cancer disease recurrence." (PMID 37427128, 2023). "Significantly higher preoperative serum IL-17A levels were recorded in women with triple-negative breast cancer compared to hormone-dependent cancer." (PMID 37427128, 2023). "A recent study reported elevated levels of Th17 cell cytokines (IL-17A and IL-17F) in T cell non-inflamed triple-negative breast cancer; thus, IL-17 was proposed as a novel prognostic biomarker for this type of cancer." (PMID 32225066, 2020). "Many studies have revealed increased levels of the cytokine IL-17A in estrogen receptor (ER)-negative or triple-negative breast cancer." (PMID 33102239, 2020).
acute lymphoblastic leukemia (7 papers, 2017 to 2025). Leukemia with an acute onset, characterized by the presence of lymphoblasts in the bone marrow and the peripheral blood. "Moreover, the upregulation of AKT and IL17A enhances the daunorubicin resistance of B cell acute lymphoblastic leukemia (ALL) cells, suggesting that daunorubicin downregulates IL17A." (PMID 39759512, 2024).
alcohol abuse (7 papers, 2014 to 2023). The use of alcoholic beverages to excess, either on individual occasions ("binge drinking") or as a regular practice. "Moreover, they found that changes in IL-6 and IL-17A plasma concentrations in alcohol use disorder patients were associated with the presence of liver and pancreatic diseases." (PMID 36830990, 2023).
ankylosis (7 papers, 2018 to 2025). Fixation and immobility of a joint. "FGF7, which has been produced in the enthesis by systemic circulating damaged skin–derived IL-17A stimulation, plays a critical role in endochondral ossification and ankylosis." (PMID 39919800, 2025). "Future trials of IL-17A inhibitors should focus on populations with early disease to determine if there is indeed a better response, the effect on the progression of ankylosis in this population, and to determine when it is appropriate to start IL-17A inhibitors therapy." (PMID 36626473, 2022). "Although the ability of IL-17A blocking to achieve a cure has been emphasized in previous studies, the regulatory mechanism by which IL-17A modulates bony ankylosis remains unknown." (PMID 29880011, 2018). "Moreover, a bispecific antibody neutralizing both cytokines, bimekizumab, was more effective than antibodies targeting either IL-17A or IL-17F implying that such dual inhibition might prevent the ankylosis observed in patients with axSpA." (PMID 34539646, 2021). "The preferential alleviation of spinal inflammation and ankylosis with IL-17A blockade in AS patients convincingly suggests that IL-17, not IL-23, is the major cytokine directing disease pathogenesis at least in axial SpA and that it is likely to be generated in an IL-23-independent manner." (PMID 34095174, 2021).
arteriosclerosis (7 papers, 2013 to 2024). A vascular disorder characterized by thickening and hardening of the walls of the arteries. "In order to observe the efficacy of IL-17A/F in arteriosclerosis, cross-mating with IL-17A, IL-17F, and IL-17A/F deficient mice was performed." (PMID 36982506, 2023). "In apoE-deficient mice, a well-characterized model for arteriosclerosis, inhibition of IL-17A signalling reduced atherosclerotic lesion formation, prevented plaque rupture, and diminished levels of circulating proinflammatory cytokines." (PMID 23468966, 2013). "In addition, no data or findings have been published on the extent to which inhibition of IL-17A or IL-17F contributes to the suppression of arteriosclerosis." (PMID 39519167, 2024). "Both IL-17A and IL-17F inhibition showed preventive effects against arteriosclerosis." (PMID 39519167, 2024). "The results also proved that treatment against IL-17A and F may ameliorate arteriosclerosis." (PMID 36982506, 2023).
bone cancer (7 papers, 2017 to 2026). A primary or metastatic malignant neoplasm affecting the bone or articular cartilage. "LTTL treatment lowered IL-17A overexpression while the intrathecal administration of IL-17A antibodies mitigated bone-cancer–evoked nociception in a dose-dependent manner, revealing that astrocyte-produced IL-17A might endorse cancer-related pain." (PMID 38730655, 2024). "In summary, LTTL treatment alleviates bone-cancer-induced nociception by downregulating TRP channel expression in DRG and IL-17A in spinal astrocytes." (PMID 38730655, 2024). "Furthermore, TLSJ was deemed valid in alleviating bone cancer-induced mechanical allodynia and thermal hyperalgesia by downregulating transient receptor potential channel expression in lumbar dorsal root ganglia and lumbar spinal cord interleukin-17A (IL-17A) in spinal astrocytes." (PMID 28837110, 2017).